PBX1 (PBX homeobox 1)
Diseases named in the same sentence as PBX1 in open-access papers (continued):
Sharing a sentence is not in itself a finding about the gene and the disease.
cancer (continued). "PBX1 is a TALE homeodomain protein involved in the development of different types of cancers." (PMID 22125492, 2011). "Thus, PBX1 is a potential therapeutic target for many cancers." (PMID 39129784, 2024). "Indeed, there is evidence that PBX1 is involved in at least five of the major hallmarks of cancer to date: sustaining proliferative signaling, activating invasion and metastasis, inducing angiogenesis, resisting cell death, and deregulating cellular energetics." (PMID 38877653, 2024). "Quantitative RT–PCR (qRT-PCR) further showed that Bcat1 (related to BCAA metabolism) or Hoxa9, Ccnt1, Pbx1, Rora and Pbx3 (related to transcriptional misregulation in cancer) were significantly reduced in P2x1-null LICs, suggesting that these genes may act as downstream targets of P2X1." (PMID 36418376, 2023). "However, some evidence suggests the opposite function of PBX1 in cancer progression." (PMID 36739270, 2023). "In addition to NBL, PBX1 was recently extensively studied in other types of cancer, and some of those studies suggested the opposite function of PBX1 in cancer progression that could be in accordance with the results we obtained." (PMID 31188873, 2019). "Finally, we demonstrate that the longitudinal increment of PBX1 levels observed throughout cancer progression are partly due to genomic events that could be potentially used to monitor disease progression in patients by non-invasive assays." (PMID 26215677, 2015). "Lending support to our study, prior research has shown that the m6A modifications of Pbx1 and E2F1 affected their stability in cancer cells." (PMID 39559922, 2025). "Analysis of the HOXA9 gene revealed a positive correlation with PBX1, PBX2, PBX3, and MEIS1 in all cancer types except for STAD among the 11 studied genes, suggesting enhanced binding of HOXA9 to the promoter region of target genes." (PMID 38904676, 2024). "In agreement with a study in which the PI3K pathway regulator PBX1 (PBX homeobox 1) is required in BC, our findings highlight the importance of PBX1 as a genetic regulator for stemness and radioresistance in cancer." (PMID 37483521, 2023). "Some of the most prevalent included known pediatric cancer fusions RUNX1::RUNX1T1 (15% AML participants), KMT2A::MLLT3/MLLT10 (12% AML), TCF3::PBX1 (4.4% ALL), and ETV6::RUNX1 (2.4% ALL)." (PMID 37323575, 2023). "PBX1 is an important member of the PBX family of proteins, the suspected group of factors in various cancers." (PMID 36046086, 2021). "Defining signatures in chromatin facilitators involved in cancer characterized some of the pioneer factors like the GATA family of proteins, TLE1 protein, and PBX1 as a valuable prognostic biomarker in BC." (PMID 36046086, 2021). "These instances are listed in the Dataset EV2 and they included, among others, RBL2, KLF5, and ARAF as homologs of cancer drivers RB1, PBX1, and BRAF, respectively." (PMID 29572294, 2018). "In an analysis of 24 breast tumours, rearrangements were found in known cancer genes including BRAF, PAX3, PAX5, NSD1, PBX1, MSI2 and ETV6, each of which is a partner in a fusion gene in several other human cancers." (PMID 24792170, 2014). "A dominant negative PBX1 protein or HOX hexapeptide motif that disrupted the interaction between PBX1 and HOX was found to significantly reduce the proliferation of these cancer cells." (PMID 22567123, 2012). "Although, ectopic expression of Pbx1 did not induce NE-like transition or morphology to the adenocarcinoma cells, however, its depletion from NE-like cancer affects neurite formation similar to Pax5 deletion." (PMID 39183332, 2024). "Endocrine system development and cancer growth-related ceRNA regulation are found in TNBC; HOXA5, SCAPER, PAK6, PBX1, PITX1, and ALOX15B are the relevant genes involved; and hsa-miR-296-5p, hsa-miR-185-5p, hsa-miR-7851-3p, hsa-miR-3187-3p, and hsa-miR-10396b-5p are the relevant miRNAs involved." (PMID 37483500, 2023).
cancer (continued). "The overexpression of PBX1 could enhance the transcription of STAT3 by directly binding to its promoter, thereby promoting cancer stem cell‐like phenotypes and increasing platinum resistance in OC patients." (PMID 35068042, 2022). "Notably, six genes—MLLT3, MEIS1, PBX1, PBX3, HOXA10, KMT2A—were found to play a role in transcriptional dysregulation in cancer." (PMID 35743243, 2022). "Therefore, PBX1 and PBX3 exhibit great potential as targets for the development of pharmacological drugs for anti‐angiogenesis in cancer treatment." (PMID 35068042, 2022). "Through the study it was concluded that the highly prospected pioneer TFs in BC, including FOXA1, TLE1, PBX1, and GATA3, possess the potential therapeutic significance and further innovations in the field could yield targeted therapy in cancer treatment." (PMID 36046086, 2021). "Given its critical role in transcriptional regulation, it comes as no surprise that PBX1 is involved in a variety of biological processes from cell fate determination during organogenesis to the development of human cancers." (PMID 22567123, 2012). "It has been reported that, in BC, PCa, and CC cells, PBX1 enhanced VCP transcription via binding its 5'‐flanking region, indicating that PBX1 might be involved in the regulation of cellular invasion and metastasis through VCP in these cancer types." (PMID 35068042, 2022).
tumor (53 papers, 2009 to 2026). "This study aimed to reveal the anti-tumor function of PBX1 in CRC and the underlying molecular mechanism." (PMID 36739270, 2023). "Pbx1 was differentially expressed in inflammation-associated pancreatic stellate cells (PaSCs) when compared to tumor-associated PaSCs." (PMID 33402862, 2020). "In contrast, our study revealed that the highest levels of PBX1 in tumor tissue are associated with poor response to induction chemotherapy, whereas PBX1 levels were decreased in non-responders." (PMID 31803613, 2019). "Overall, these data suggest that PBX1 underlies the expression of EGF dependent genes involved in aggressive tumour progression." (PMID 26215677, 2015). "In the microarray analysis, pre-B-cell leukemia transcription factor 1 (Pbx1) was 1.7-fold upregulated in inflammation associated stellate cells compared to tumor associated stellate cells." (PMID 20416094, 2010). "PBX1 has also been implicated in some neoplastic diseases, so there may be a risk of tumorigenesis in research on embryonic development and regenerative medicine." (PMID 36794159, 2023). "Furthermore, the survival analysis clearly demonstrated that high levels of PBX1 in tumor tissue are significantly associated with a worse clinical prognosis." (PMID 31803613, 2019). "PBX1 is also required for the expression of genes associated with tumour progression." (PMID 26215677, 2015). "In vivo, xenograft experiments demonstrated that PBX1 overexpression suppressed tumor growth, which was further augmented by BCL2L1 knockdown." (PMID 42086530, 2026). "PBX1 exhibits a “double-edged sword” property in tumors, exhibiting either oncogenic or tumor-suppressive roles, depending on the tissue type and molecular context." (PMID 40299657, 2025). "Knockdown of YTHDC1, POLR2B, and PBX1 reduced xenograft tumor volume and prolonged the survival of nude mice." (PMID 39090090, 2024). "PBX1 is a transcription factor that can promote the occurrence of various tumors and play a reg-ulatory role in tumor growth, metastasis, invasion, and drug resistance." (PMID 39129784, 2024). "By acting as a pioneer factor, PBX1 is essential for the ERα-mediated transcriptional response, promoting greater tumor proliferation and aggressiveness." (PMID 38404687, 2024). "In myeloproliferative neoplasms, PBX1 influences the stem cell transcriptional program, driving tumor progression." (PMID 39129784, 2024). "Most of the time, PBX1 as an oncogene promotes the proliferation of tumor cells, induces angiogenesis, and participates in the occurrence and development of tumors." (PMID 37006624, 2023). "PBX1 functions in mammalian kidneys include promoting tumor progression, regulating basic developmental processes, and adjusting glomeruli vascularization." (PMID 37006624, 2023). "Taken all together, these results concluded that TRIM26 promotes NSCLC tumor growth by suppressing PBX1 via the ubiquitin-proteasomal pathway." (PMID 37324936, 2023). "Seven genes (CACNB2, IL34, CGNL1, CNTN3, GAS7, HOPX, and PBX1) regulated by miR-31-5p and miR-31-3p were identified as putative tumor suppressors." (PMID 34201353, 2021). "This suggests that PBX1 induces EMT by increasing the expression of downstream tumor growth and angiogenic factors." (PMID 28514754, 2017). "This hydrophobic interaction between PBX1 and the hexapeptide motif is essential for tumor growth and angiogenic factor expression, and thus is essential for PBX1-dependent tumorigenesis and EMT induction of GC." (PMID 28514754, 2017). "Again, PBX1 retained significance in a multivariate analysis including lymph node status, grade, tumor size and PBX1 expression (HR = 1.27, p = 0.0173)." (PMID 26215677, 2015).
tumor (continued). "In agreement, we found that normal ductal cells adjacent to tumor tissue have very low PBX1 staining (stronger stained cells are myoepithelial cells)." (PMID 26215677, 2015). "For the METABRIC dataset, PBX1 expression retained significance in a multivariate analysis including lymph node status, grade and tumor size (HR = 1.27, p = 0.0173)." (PMID 26215677, 2015). "As the role of PBX1 in human solid tumors is emerging, the target genes directly controlled by PBX1 reported herein will serve as footsteps for deciphering how PBX1 contributes to tumor development." (PMID 22567123, 2012). "We have focused on one PBX1 direct target gene, MEOX1, and demonstrated its involvement in PBX1-mediated tumor cell growth as well as its direct interaction with PBX1." (PMID 22567123, 2012). "PBX1 stimulates NFIB, an oncogene linked to several neoplasms, in HL cell lines, as demonstrated by elevated NFIB expression levels in the presence of PBX1 and diminished expression following PBX1 knockdown, thereby demonstrating PBX1’s direct regulatory effect on NFIB transcription." (PMID 41226583, 2025). "In this tumor, lack of PBX1 was shown to cause absence of DCDC2 suppression, resulting in increased WNT signaling and increased spindle function, which in turn lead to cell proliferation and metastasis." (PMID 38404687, 2024). "This may be one of the mechanisms whereby PBX1-related tumor cells escape death, and may be a new therapeutic target." (PMID 39129784, 2024). "Moreover, the IB analyses on tumor tissues from xenografts showed that overexpression of TRIM26 decreased PBX1 and RNF6, while knockout of TRIM26 led to upregulation of PBX1 and RNF6." (PMID 37324936, 2023). "As reflected by tumor volume and weight, PBX1 significantly suppressed tumor growth." (PMID 36739270, 2023). "Furthermore, in vitro and in vivo experiments verified the inhibitory effect of PBX1 on tumor proliferation and metastasis in CRC." (PMID 36739270, 2023). "Thus, the tumor microenvironment that promotes chemoresistance in OC cells is correlated to the upregulation of PBX1." (PMID 37175439, 2023). "Overexpression of PBX1 suppresses tumor growth and metastasis in vitro and in vivo." (PMID 36739270, 2023). "Collectively, PBX1 suppressed CRC tumor proliferation and metastasis both in vitro and in vivo." (PMID 36739270, 2023). "TRIM26 interacts with PBX1 and mediates its K48-linked polyubiquitination and proteasomal degradation therefore inhibiting PBX1 transcriptional activity and promotes NSCLC cell proliferation and tumor survival." (PMID 37324936, 2023). "This study has several limitations: although we have recently verified the role of the E2F6 ceRNA network in the epigenetic control of miR-193a, the role of such a network in the regulation of PBX1 and the subsequent anti-tumor immune response requires experimental validation." (PMID 35216394, 2022). "In addition, we performed IHC staining with both anti-SPHK1 and anti-PBX1 antibodies on NSCLC tumor specimens to measure the correlation between the two molecules." (PMID 36361531, 2022). "Meanwhile, the Erk pathway was also involved in the regulation of PBX1 expression, and whether the Erk pathway was involved in PBX1 mediated other malignant phenotypes and pathological processes of tumor cells." (PMID 36361531, 2022). "In other studies, it was found that HOXB5 protein could bind with its cofactor PBX1 to induce apoptosis, thus delaying tumor progression." (PMID 34306077, 2021). "Therefore, Pbx1 can have a dual role as an oncogene or tumor suppressor, depending on its binding partner (Mesi1 or Prep1, respectively)." (PMID 34698191, 2021). "Indeed, the Pbx-interacting regions (HR1 and HR2 domains) are required in both the oncogenic function of Meis1 and in the tumor-suppressive role of Prep1, i.e., both activities are performed by a complex of either protein with Pbx1." (PMID 34698191, 2021).
tumor (continued). "Moreover, while Meis1, Meis2, and Pbx1 expressions are downregulated, Hoxa9 expression is upregulated during the tumor initiation and progression of PC." (PMID 33402862, 2020). "In addition, the inhibition of miR-198 leads to the upregulation of Pbx-1 and VCP, which causes tumor progression." (PMID 33402862, 2020). "Results of IHC analyses of DDX39A, HMGA1, HMGA2, HOXC9, and PBX1 expression in tumor samples." (PMID 31188873, 2019). "Although previous studies have shown that PBX1 can regulate the transcriptional activity of specific genes cooperatively with the HOX hexapeptide, the role of PBX1 in the regulation of tumor growth and angiogenic factors remains unclear." (PMID 28514754, 2017). "Furthermore, the Phe252 residue in the TALE homeodomain of PBX1 is critical in the expression of tumor growth and angiogenic factors in GC cells." (PMID 28514754, 2017). "We then reasoned that the emergence of PBX1 CNV may have contributed to tumor progression and used PBX1 amplification in cfDNA as a classifier to stratify patients based on time to relapse or overall survival." (PMID 26215677, 2015). "Notably, we demonstrate that PBX1 amplification can be identified in tumor derived-circulating free DNA of ERα-positive metastatic patients." (PMID 26215677, 2015). "Finally we reveal that PBX1 upregulation in aggressive tumours is partly mediated by genomic amplification of the PBX1 locus." (PMID 26215677, 2015). "Similarly, the protein expression of Pbx1 was also 64% higher in stellate cells derived from inflammatory pathologies compared to that of tumor derived stellate cells (p = 0.70)." (PMID 20416094, 2010). "PBX1 expression levels tend to be increased in inflammatory- vs. tumor- stellate cells." (PMID 20416094, 2010). "Furthermore, PBX1 may influence tumor-promoting inflammation and immune evasion, although the evidence supporting these claims is less established." (PMID 41226583, 2025). "Moreover, depletion of PBX1 inhibits tumor proliferation in the presence of estrogenic stimuli." (PMID 38404687, 2024). "In addition to acting on primary tumor cells, PBX1 also plays a role in promoting metastasis." (PMID 38404687, 2024). "Moreover, it has been reported that PBX1 promotes tumor progression as an oncogene." (PMID 37006624, 2023). "Thus, both Meis1 oncogenic and Prep1 tumor-suppressing activities require interaction with Pbx1." (PMID 34698191, 2021). "Additionally, we observed that PBX1 promotes the expression of tumor growth and angiogenic factors." (PMID 28514754, 2017). "Thus, tumor growth and angiogenic factor expression increased during PBX1-dependent EMT induction." (PMID 28514754, 2017). "The circRNA signature in childhood TCF3::PBX1 subtype B-cell ALL, has identified cirANSK1B, cirBARD1, and cirMAN1A2 as overexpressed and potential biomarkers for prognosis and tumor detection." (PMID 40806675, 2025). "The transcription factors PBX1 and FLI1, known regulators involved in angiogenesis, were observed to be upregulated in TC-ECs from tumour tissue, further emphasising their roles in endothelial differentiation and vascular remodelling." (PMID 40427675, 2025). "Conversely, suppressing PBX1 enhances the radiosensitivity of esophageal squamous cell carcinoma by targeting STAT3, inhibiting tumor cell proliferation and tumor growth." (PMID 39129784, 2024). "In summary, the present study demonstrates TRIM26 is a first reported ubiquitin ligase of PBX1 and elucidates the detailed mechanism under TRIM26 promotes NSCLC cell proliferation and tumor growth by targeting PBX1." (PMID 37324936, 2023). "In conclusion, TRIM26 is a ubiquitin ligase of PBX1 and it promotes while PBX1 inhibits NSCLC tumor growth." (PMID 37324936, 2023). "PBX1-rG4 edited cell lines showed no dependence on rG4-stabilizing compounds, and immunohistochemistry of normal and tumor tissues revealed that DHX9 absence corresponded to PBX1 absence." (PMID 39940956, 2025).
tumor (continued). "Furthermore, the transcription factors PBX1 and FLI1 exhibited higher activity in the tumour-derived T1 cluster, suggesting their potential regulatory roles in driving these downstream changes." (PMID 40427675, 2025). "We did not observe classical oncogenic features in standard tissue culture experiments, suggesting a defining role of cell lineage/cell‐type rather than an oncogenic/tumour suppressor role for PBX1 in CCA." (PMID 38877653, 2024). "In the tumor orthotopic transplantation experiment, the survival analysis of the nude mice showed that the individual knockdown of YTHDC1, POLR2B, or PBX1 could prolong survival." (PMID 39090090, 2024). "Taken together, our findings exhibit the vital role of the SPHK1/S1PR3/PBX1 axis in regulating the cell cycle of NSCLC, and targeting SPHK1 may develop a therapeutic effect in tumor treatment." (PMID 36361531, 2022). "Among them, PBX1, PBX2, PBX3 and PBX4, which are members of the PBX gene family, may be involved in tumor cell development." (PMID 33535170, 2021). "Nevertheless, the most interesting result was found for PBX1: non-responders had significantly higher expression of this protein in the initial tumor samples." (PMID 31803613, 2019). "In general, high levels of DDX39A and PBX1 were found in all tumor samples while HMGA proteins showed poor (HMGA1) or no (HMGA2) endogenous expression in tumor cells." (PMID 31188873, 2019). "HOXB9 mRNA expression is reduced in some PBX1-expressing GC tissues, and the occurrence of a moderately diminished relationship between PBX1 and HOXB9 expression indicates that PBX1 and HOXB9 may be considered tumor markers when attempting to determine GC malignancy." (PMID 28514754, 2017). "We supposed that the dramatically suppressed of PBX1 in CRC causing that the source of PBX1 mRNA in silico was mainly from tumor stromal cells and infiltrative immune cells so that the PBX1 level in TCGA could not reflect the actual PBX1 expression in tumor cells." (PMID 36739270, 2023). "Unfortunately, romidepsin and T417 as tumor targeting drugs and targeting the YTHDC1/circPOLR2B/POLR2B/PBX1 axis were not examined in the present study." (PMID 39090090, 2024).